IFNAR1 (interferon alpha and beta receptor subunit 1)
Diseases named in the same sentence as IFNAR1 in open-access papers (continued):
Sharing a sentence is not in itself a finding about the gene and the disease.
melanoma (46 papers, 2011 to 2025). A malignant, usually aggressive tumor composed of atypical, neoplastic melanocytes. "In our previous study, we demonstrated that loss of IFNAR1 following exposure to melanoma-derived TEVs resulted in loss of CH25H." (PMID 38405101, 2024). "Collectively, our results suggest that the BRAFV600E mutation in melanoma, potentially by upregulating the IFNAR1/2, renders distinct susceptibility to antitumor therapies that induce IFN-1 pathway, such as the ICD-inducer PDT." (PMID 39061208, 2024). "Data indicated that melanoma carcinogenesis was promoted in the IFNAR1 deficient host and the resulting tumors were spontaneously metastatic." (PMID 35269844, 2022). "In a previous study, we demonstrated that cancer cell-derived EVs (TEVs) from melanoma cells and melanoma patients downregulated the type 1 interferon receptor subunit 1 (IFNAR1), resulting in loss of the interferon-stimulated gene (ISG) cholesterol-25 hydroxylase (CH25H)." (PMID 38405101, 2024). "Specifically, they demonstrate that Poly(I:C)-induced RLH activation inhibits melanoma and other metastasis via a MAVS-dependent mechanism and that the melanoma inhibitory effects of Poly(I:C) are associated with the induction of Type I IFNs and dependent on IFNAR1." (PMID 27198666, 2016). "This coincides with our previous data demonstrating that EO771 cells release TEVs that downregulate IFNAR1 in peripheral blood leukocytes (PBLs), splenocytes, and lung tissue, similar to TEVs from melanoma cells." (PMID 38405101, 2024). "Previous studies demonstrated that reserpine prevents loss of IFNAR1 and CH25H expression in melanoma to suppress the development of metastasis." (PMID 38405101, 2024). "In melanoma, BRAF activation and mutations in phosphoinositide 3-kinase (PI3K) can downregulate IFNAR1, which inhibits the tumor-suppressive role of IFN signaling." (PMID 37374093, 2023). "Our results showed that depleting IFNAR1 in astrocytes significantly decreased brain metastatic outgrowth of breast cancer and melanoma in both female and male mice." (PMID 37149684, 2023). "Constitutive ERK signaling was shown to downregulate IFNAR1 expression in BRAF mutant melanomas, which made the tumors resistant to type I interferon-mediated growth inhibition." (PMID 37803324, 2023). "The indispensable role of IFNAR is additionally highlighted in a study that showed the downregulation of IFNAR1 promotes melanoma progression." (PMID 37304294, 2023). "The inhibitory effect of both mrIfn-β and mrIfn-γ in Igf2bp1 gene knockout cells was rescued by Ifnar1 knockout in melanoma cell line PVMM, which shares a genetic background with the wild type SM1 cell line." (PMID 37503349, 2023). "MMP2 is secreted from melanoma cells and then cleaves IFNAR1, leading to inactivation of DCs, induction of T helper 2 (Th2) cell polarization and low levels of STAT1 phosphorylation." (PMID 36104718, 2022). "The role of type I IFNs in the carcinogenesis and the progression of BRAF-mutant melanoma was analyzed in a genetically manipulated mouse model where IFNAR1 was knocked out." (PMID 35269844, 2022). "MEK inhibitor (MEK-I) administration would inhibit the reactivation of the MAPK pathway induced by BRAF-I resistance and, as a result, would restore IFNAR1 expression on melanoma cells when it is downregulated by ERK reactivation." (PMID 33407577, 2021). "We, and others, have shown that BRAF inhibitors (BRAF-I) enhance the antiproliferative and immunomodulatory effects of IFN-α on BRAFV600E melanoma cells because the inhibition of ERK activation by BRAF-I upregulates IFNAR1 expression on melanoma cells." (PMID 33407577, 2021). "MAPK pathway activation is also known to downregulate the expression of type I IFN-α receptor-1 (IFNAR1), which mediates the effects of IFN-α, a cytokine used for the adjuvant treatment of high-risk melanoma." (PMID 33407577, 2021).
melanoma (continued). "We assessed the expression of IFNAR1 in MDSC from transplantable models of B16 melanoma, LLC lung carcinoma, CT26 colon carcinoma, and genetically engineered models of melanoma (RET) and pancreatic cancer (KPC)." (PMID 33741967, 2021). "The mean percentage of melanoma cells expressing IFNAR1 was 48.0 (± 29.5) in sections obtained before treatment with vemurafenib + PEG-IFN-α-2b, and 46.0 (± 19.5) in sections from post-treatment biopsies." (PMID 33407577, 2021). "In particular, a low number of melanoma cells expressing IFNAR1 in pretreatment lesions was correlated with a better clinical outcome." (PMID 33407577, 2021). "Tumor models established using IFNAR1-deficient tumor cells (i.e., MC38 colorectal carcinoma, B16F10 melanoma, and KPC pancreatic cancer cells) exhibited improved therapeutic responses to IR in a CD8+ T cell-mediated manner." (PMID 33238631, 2020). "The degradative loss of membrane‐bound IFNAR1 and suppression of IFN‐I signaling are a common event in human melanoma progression." (PMID 32918364, 2020). "Conversely, the expression of a stable IFNAR1 mutant in melanoma cells abrogated melanoma metastasis, with tumor cells showing increased IFN‐I signaling and senescence markers." (PMID 32918364, 2020). "Pharmacologic inhibition of either RAF or MEK1 stabilized IFNAR1 in melanoma cells and decreased their tumorigenicity." (PMID 25709607, 2015). "In addition, both systematic Ifnar1 blocking and KO of tumor cell–intrinsic Ifnar1 reversed the growth retardation of Usp5-depleted murine B16 melanomas." (PMID 41321309, 2025). "In our third model, we challenged Ifnar1–/– mice with B16-Ifnar1–/– melanoma cells." (PMID 38861331, 2024). "In our second model, we challenged Ifnar1–/– mice with B16 melanoma cells." (PMID 38861331, 2024). "Further studies have shown that the in vitro and in vivo inactivation of type I IFN signaling by using shIFNAR1 cells and IFNAR1-null mice, respectively, overcome oncogene-induced senescence, a tumor-suppressive signal that protects DNA-damaged cells from the onset of melanoma." (PMID 37374093, 2023). "Restoration of IFNAR1 signaling in BRAF mutant melanoma cells attenuated tumor growth in vivo." (PMID 35269844, 2022). "In a phase I study, adult patients with advanced BRAFV600-mutated melanoma were treated with vemurafenib + PEG-IFN-α-2b or vemurafenib + cobimetinib + PEG-IFN-α-2b, to assess the safety of the combination and the upregulation of IFN-α/β receptor-1 (IFNAR1)." (PMID 33407577, 2021). "Of note, although IFN-I was not required for the induction of resistance, it helped sustain ICB resistance, as additional IFNAR1 ablation on top of IFNGR1 deletion promoted a greater therapeutic response in ICB-resistant melanoma, as compared to IFNGR1 deletion alone." (PMID 34830176, 2021). "However, reactivation of the MAPK pathway caused by BRAF-I resistance is expected to reactivate ERK activity, which, in turn, would downregulate IFNAR1 expression on melanoma cells." (PMID 33407577, 2021). "Regarding OS, patients with a percentage of melanoma cells expressing IFNAR1 of ≤ 35% had a median OS of 31.0 months (range: 19.8–42.2 months), while patients with a percentage of stained melanoma cells expressing IFNAR1 of > 35% had a median OS of 5.0 months (p = 0.02)." (PMID 33407577, 2021). "In a study on melanoma cells, the inflammatory cytokines interleukin 1α (IL-1α) and TNFα, secreted by melanoma cells, but no other cytokines, were reported to stimulate the phosphorylation, and subsequent ubiquitination and degradation of IFNAR1." (PMID 32604862, 2020). "Consequently, IFNAR1 knockout mice showed accelerated melanoma development after induction of a conditional BrafV600E allele." (PMID 32918364, 2020). "Furthermore, the MAPK activation downregulates interferon alpha receptor 1 (IFNAR1) signaling; accordingly, BRAFi reverses IFNAR1 inhibition in melanoma biopsies, providing a rationale for the combination of interferon alpha (IFN-α) with BRAFi." (PMID 32731406, 2020).
melanoma (continued). "The destabilization and downregulation of IFNAR1 in BRAFV600E melanomas might account for the suboptimal anti-proliferative effects of IFN." (PMID 25709607, 2015). "However, analysis of IFN-treated human melanoma tumor samples showed only a trend of lower IFNAR1 with a poorer outcome of patients, suggesting that the host may also participate in the regulation of IFN signaling." (PMID 35269844, 2022). "Both melanoma cell lines showed again a very comparable expression pattern of antiviral genes, with low expression of most genes, except for STING1, IFNAR1, IFNAR2, and IFIH1, which were moderately expressed." (PMID 40955425, 2025). "In a murine melanoma model, the topical application of IMQ leads to TRAIL and GrB secretion and resulted in tumor clearance in a TLR7/MyD88- and IFNAR1-dependent manner." (PMID 32054102, 2020). "IFNAR1 depletion did not alter the tumorigenicity in vivo in colon adenocarcinoma, melanoma, pancreatic ductal adenocarcinoma or Lewis lung carcinoma models." (PMID 36571986, 2023). "Downregulation of IFNAR is found during tumor development in melanoma patients and expression of a non-degradable IFNAR1 mutant in mice was shown to delay the formation and progression of melanoma and increase responsiveness to BRAF or PD-1 inhibitors in vivo." (PMID 33801234, 2021). "In addition, Poly(I:C) inhibition of tumor-induced Chi3l1 was also dependent on IFNAR1 and the ability of Poly(I:C)-induced RLH activation to inhibit melanoma metastasis was significantly decreased in mice with null mutations of IFNAR1." (PMID 27198666, 2016). "Experiments with human malignant melanoma tissues and cell lines have shown that proinflammatory cytokines, such as IL-1α/β and TNF-α, produced by melanoma cells activate p38 kinase to promote the IFN-α/β-independent pathway of IFNAR1 degradation." (PMID 24516470, 2014). "In our first model, we challenged mice with B16 melanoma cells lacking IFNAR1 (B16-Ifnar1–/–)." (PMID 38861331, 2024). "We further compared the expressions of IFNAR1 and IFNAR2 in normal skins, nevus tissues, and melanoma tissues using a published dataset (GSE3189) and found that the expressions of IFNAR1 and IFNAR2 are significantly higher in melanoma as compared to normal skin and nevus tissues." (PMID 35145233, 2022). "Therefore, IFNAR1 could serve as an important mediator of the direct and indirect effect of IFN-I therapy, which has been validated in the context of myeloid-derived suppressor cells and melanoma cells." (PMID 36104718, 2022). "We found that the expression of IFNAR2, but not IFNAR1, is correlated with the enrichment of infiltrated CD8+ T cells in the metastatic melanoma tissue microenvironment." (PMID 35145233, 2022).
lupus (44 papers, 2011 to 2026). "IFNAR1 regulated anticytoplasmic and anti-RNA specificities and its deficiency prevented the exacerbation of clinical disease in this lupus model." (PMID 24741625, 2014). "Anifrolumab (Saphnelo®, Astra Zeneca AB), is a humanized IgG1k monoclonal antibody therapy that binds to a subunit of the IFN-I receptor (IFNAR1) and was recently approved to treat adult patients with Systemic Lupus Erythematosus (SLE)." (PMID 39441221, 2024). "We have examined the effect of IFNAR1 blocking antibodies on alloimmunization of PrWT mice that have already developed a lupus-like phenotype." (PMID 38288124, 2023). "To functionally test this, we blocked IFNγ production using IL-18BP and type I IFN signaling using the anti-IFN α receptor 1 (IFNAR1) antibody anifrolumab, which is in clinical trials to treat systemic lupus erythematosus." (PMID 35930640, 2022). "Anifrolumab, a monoclonal antibody of IFNα receptor 1 (IFNAR1), is used to treat inflammatory autoimmune disease systemic lupus erythematosus (SLE), in which the immune system attacks its own tissues by blocking the pro-inflammatory type I IFNs pathway." (PMID 34445373, 2021). "In contrast to our findings, studies reported that crossing two other lines of lupus-prone mice to IFNAR1-KO mice reduced the levels of autoantibodies and glomerulonephritis and, therefore, increased life span." (PMID 27807192, 2016). "This approach is supported by a study showing that deletion of Ifnar1 prevented severe disease in at least two lupus-prone strains." (PMID 26137972, 2015). "Concomitant with upregulation of Sn in diseased renal tissues of NZBWF1 mice, we also observed increased expression of the Ifnar1 gene, similar to what has been reported previously in lupus-prone MRL/lpr mice as part of the interferon signature." (PMID 24286366, 2013). "Moreover, monoclonal antibody therapy targeting the IFN alpha receptor 1 (IFNAR1) elicited HSV-2 acute hepatitis in a patient with systemic lupus erythematosus (SLE), while AAN-I-IFNs were found in a patient with HSV-2 acute hepatitis." (PMID 41348319, 2026). "For instance, filgotinib and upadacitinib, both selective inhibitors of JAK1, are promising candidates in the future, as well as the monoclonal antibody to type I IFN receptor subunit 1 (IFNAR1) anifrolumab, which showed promising effects in systemic lupus erythematosus." (PMID 35418997, 2022). "Anifrolumab is a monoclonal antibody targeting the type I interferon receptor (IFNAR1) approved for the therapy of systemic lupus erythematosus (SLE)." (PMID 41159030, 2025). "Anifrolumab (Saphnelo) is a fully human IgG1 targeting type I interferon receptor subunit 1 (IFNAR1) approved in 2021 for moderate to severe systemic lupus erythematosus (SLE)." (PMID 41219972, 2025). "Given the well documented role of IFNα/β in the pathogenesis of autoimmune disorders (including systemic lupus erythematosus, psoriasis, and Type 1 diabetes mellitus), temporal downregulation of IFNAR1 might play an important role in protecting the host from such autoimmune reactions." (PMID 21695243, 2011). "The humanized anti-IFNAR1 antagonist mAb, anifrolumab, was recently approved by the US FDA for treatment of systemic lupus erythematosus." (PMID 36291750, 2022). "This revealed that three prioritised lupus genes (USP18, STAT1, IFNA1-17) were shared with the 13 category I genes (IFNAR1/2 signal transduction proteins) and four prioritised genes (IRF1/5/8 and OAS1) were shared with the 38 category II genes (transcriptional targets of interferon response)." (PMID 41038828, 2025).
influenza (38 papers, 2011 to 2025). An acute viral infection of the respiratory tract, occurring in isolated cases, in epidemics, or in pandemics; it is caused by serologically different strains of viruses (influenzaviruses) designated A, B, and C, has a 3-day incubation period, and usually lasts for 3 to 10 days. "This includes herpes viruses (HSV, VZV, EBV), HPV and molluscum for DOCK8-deficiency, and HSV1, HSV2, SARS-CoV2, influenza and live attenuated viral vaccines for IFNAR1-deficiency." (PMID 39098944, 2024). "To first assess the potential of 4’-FlU to pharmacologically manage influenza in high-risk hosts, we infected interferon α/β receptor knockout (IFNAR1 KO) and V(D)J recombination activation gene RAG-1 KO mice with pdmCa09." (PMID 37068076, 2023). "While cell surface receptor for type I IFNs consists of two distinct subunits (IFNAR1 and IFNAR2), almost all research on determining the role of type I IFNs in susceptibility to influenza and subsequent BSIs has focused solely on the involvement of IFNAR1 (using Ifnar1−/− mice)." (PMID 30473701, 2018). "To test in vivo whether lack of IFN responsiveness in lung epithelia impacts the disease course of influenza infection, we generated bone marrow chimeras where B6 wild-type bone marrow was grafted into either wild-type or IFNAR1/IL28Rα deficient hosts." (PMID 24278020, 2013). "These inflammation-biased gene expressions by Ly6Cint monocytes may explain the higher susceptibility of Ifnar1−/− mice to influenza infection." (PMID 21383977, 2011). "Our findings suggest that IFNAR1- or IFNAR2-deficient patients may be prone to critical influenza." (PMID 36112363, 2022). "Furthermore, influenza infection causes prominent inflammation in Apoe−/− mice, indicating that a defect in lipid metabolism in Ifnar1−/− mice might contribute to worsen inflammation." (PMID 21383977, 2011). "In PBS-12SF chicken cells, shRNA knock-down of IFNAR1 resulted in higher production of influenza H1N1 and decreased expression of ISGs suggesting a limitation in the antiviral mechanisms controlled by IFNs." (PMID 35056582, 2022). "Neutrophils also infiltrated in both young and aged mice during influenza infection, but their numbers were unaltered by anti‐IFNAR1 treatment." (PMID 34547174, 2021). "For example, miR146a, and miR26a promote type I IFNs and reduce influenza infection in experimental models, whereas miR29a reduces IFNAR1 and has the opposite effect." (PMID 32265937, 2020). "To summarize, during S. Typhimurium-induced colitis, prior infection with influenza alters gut immune response promoting anti-inflammatory cytokines and reducing pro-inflammatory cytokines through an IFNAR1-dependent mechanism." (PMID 27149619, 2016). "In summary, our findings indicate that differences in the fecal microbiota between WT and Ifnar1-/- mice prior to influenza infection are insufficient to explain the PR8-mediated changes in specific endogenous bacterial population in WT mice." (PMID 27149619, 2016). "Probably due to the antagonistic effect of influenza virus NS1 protein on type I IFN activity and the redundant role of IFN-lambda in viral clearance, BALB/c IFNAR1−/− mice have been shown to be as resistant to influenza infection as WT controls." (PMID 25500584, 2014). "The number of Ly6Chi monocytes stored in the spleen was also decreased in Ifnar1−/− mice compared to WT mice, whereas the number of neutrophils was comparable before influenza infection." (PMID 21383977, 2011). "Of note, WT BM reconstituted Ifnar1−/− chimeric mice with increased numbers of Ly6Chi monocytes survived longer than influenza-infected Ifnar1−/− mice." (PMID 21383977, 2011). "Staining specifically for myeloperoxidase (MPO), most abundantly present in the granules of neutrophils, confirmed increased numbers of MPO+ neutrophils in the lung of Ifnar1−/− mice after influenza infection." (PMID 21383977, 2011).